EGFR (epidermal growth factor receptor)
Diseases named in the same sentence as EGFR in open-access papers (continued):
Sharing a sentence is not in itself a finding about the gene and the disease.
tumor (continued). "The application of an exponential decrease model in cytotoxicity by EGFR-TKI treatments appeared to fit for EGFR-TKI-induced tumor cell reduction." (PMID 27708242, 2016). "Our result showed that tumor in wt-EGFR mice expressed equivalent or higher amount of EGFR than H3255 cell line, and much higher amount than HCC827." (PMID 26646697, 2016). "hSulf-1 can inhibit the formation of the HB-EGF/HSPG/EGFR complex and thus exert anti-tumor activity." (PMID 27806323, 2016). "Thisview is also corroborated by the high expression of PACAP, VIP, VIPRs, HIFs, and EGFR inthe frozen tumor sample." (PMID 27303300, 2016). "In fact, we found that 1 T SMF can suppress the mTOR inhibitor-induced EGFR reactivation and enhance the anti-tumor efficacy of mTOR inhibitors and EGFR inhibitor afatinib." (PMID 27223425, 2016). "Some randomized samples were used to detect tumor-associated transcripts, such as prostate-specific membrane antigen (PSMA), prostate-specific antigen (PSA) and epidermal growth factor receptor (EGFR), in the isolated CTCs." (PMID 27479125, 2016). "In summary, our study demonstrates that TAZ promotes cell proliferation and tumor formation in GBM cells by activating the EGFR/AKT/ERK pathway." (PMID 27167112, 2016). "Currently EGFR inhibitors are in phase II clinical trials and show efficacy to inhibit tumor growth in xenograft models." (PMID 26840086, 2016). "The stimulation of EGFR in HNSCC results in cell proliferation, a reduction in apoptosis and increased tumor cell metastasis, and is associated with poor clinical outcome in this malignancy." (PMID 27886147, 2016). "Iron oxide core nanoparticles were coated with cetuximab, an anti-epidermal growth factor receptor antibody, for specific tumor targeting." (PMID 28774062, 2016). "In contrast, phylogenetic analysis of an EGFR‐amplified tumor showed an up‐regulation of pro‐invasive genes." (PMID 27888226, 2016). "EGFR(2R)-lytic hybrid peptide showed a potent cytotoxicity as well as anti-tumour effect against OSCC cells both in vitro and in vivo." (PMID 26956916, 2016). "FAM83 protein family only contain a domain (DUf1669) with weak homology to a phospholipase D, and the elevated FAM83 member expression in tumor increase phospholipase D activity resulting in hyperactivation of epidermal growth factor receptor (EGFR)." (PMID 27769048, 2016). "Particularly, the combination of gemcitabine followed by gefitinib (an inhibitor of the epidermal growth factor receptor) has been found be more effective in controlling tumor growth than the reverse drug schedule." (PMID 27224913, 2016). "EGFR has been shown to be important for cell proliferation and migration as well as in tumor progression." (PMID 27830833, 2016). "A 1 by 1-cm tissue sample (either an EGFR-positive tumor xenograft or EGFR-negative normal mouse tissue) was placed on a glass slide." (PMID 26878888, 2016). "It has demonstrated blocking ability against the binding of EGF and TGF-alpha to EGFR, and has observed inhibitory activity on tumor cell growth, angiogenesis, and apoptosis." (PMID 27050148, 2016). "The translocation of phosphorylated EGFR to the nucleus is an integral component of the cascade that results in tumor resistance to EGFR therapeutic agents." (PMID 27462789, 2016). "In eight cases, tumor biopsies conducted after treatment were available, and there were 62.5% and 37.5% concordance rates for EGFR and KRAS, respectively." (PMID 27589834, 2016). "Epidermal growth factor (EGF) is the first ligand that is used to improve tumor cells specificity of SubA for the overexpression of epidermal growth factor receptor (EGFR) on tumor cell surface." (PMID 27585649, 2016). "It is also believed that the interplay between notch and EGFR is involved in the genesis and maintenance of tumor cells in various cancers including GBM." (PMID 27118928, 2016).
tumor (continued). "The data showed forty five proteins were found to be differentially expressed comparing tumors vs non-tumor tissues, of which EGFR and cdc2p34 were correlated with muscle invasion and histological grade." (PMID 27626805, 2016). "Kaplan–Meier analysis was not meaningful for total EGFR or HER2 expression since this ER+ series contained very few highly HER2 or EGFR expressing tumours." (PMID 26178788, 2016). "GBM is often associated with mutation and amplification of the epidermal growth factor receptor (EGFR) gene and consequently, the importance of EGFR signaling for tumor development and maintenance has gained much attention." (PMID 27118928, 2016). "As expected, we found that EGFR protein levels were higher in tumor tissues (1.04 ± 1.38 to 0.32 ± 0.56, P = 0.0003)." (PMID 27203390, 2016). "EGFR over-expression can be utilized to selectively deliver high quantities of polyinosine/polycytosine (polyIC) into tumor cells, while leaving normal cells unaffected, due to the low amounts of polyIC delivered." (PMID 27598772, 2016). "In recent years, EGFR-targeted therapy has been reported to not only inhibit tumor cells, but also reduce the secretion of GM-CSF, CCL3, TGF-α, bFGF, and VEGF, further affecting the tumor microenvironment." (PMID 27683110, 2016). "MMP2, as the downstream molecule of MEK-1/ERK1/2 pathway, is regulated by EGFR and plays important role in tumor invasion." (PMID 27830833, 2016). "Previous research has proved that disrupting the glycosylation of EGFR reduces both cellular protein levels and receptor activity in tumor cells through retention of the receptors in the ER/Golgi compartments." (PMID 26824318, 2016). "Both the single and combination agents reduced tumor size, and induced Ki67 downregulation as well as phospho-EGFR." (PMID 27129152, 2016). "Based on these reported studies, the relationship between mutant EGFR status and PD-L1 expression in tumor tissues is inconclusive." (PMID 27833557, 2016). "Western blot analysis performed on tumor samples indicated that the EGFR level remained lower at the time when tumors were harvested." (PMID 26820293, 2016). "The relationships between each protein expression level and the clinicopathologic factors were examined, only AREG/EGFR co-expression was significantly related to tumor differentiation (P = 0.032)." (PMID 27391842, 2016). "Compared to an established tumour target like EGFR and Her2/Neu this number is only marginally less." (PMID 27842504, 2016). "Recurrent tumor disease often shows higher radiation resistance and higher expression of the epidermal growth factor receptor (EGFR)." (PMID 26792072, 2016). "Simultaneous targeting on VEGF and EGFR does show significant inhibition on CRC tumor growth and angiogenesis in mice model, and these effects are mainly attributed to suppression of the AKT and ERK signaling pathways." (PMID 27729020, 2016). "A growing body of data points out that various miRNAs impede the growth of gefitinib-resistant tumours both in vitro and in vivo, meaning these effects can be attributed largely to the manipulation of EGFR/MET pathway and apoptotic cell death." (PMID 26891293, 2016). "This is consistent with the clinical efficacy of first generation EGFR-TKIs combined with a MET inhibitor for the control of tumor growth in these patients." (PMID 27259997, 2016). "In contrast to the studies performed using cell lines and/or in vivo mouse models, the correlation between mutant EGFR status and PD-L1 expression in tumor tissues in NSCLC patients seems to be controversial." (PMID 27833557, 2016).
tumor (continued). "In contrast to HNSCC, EGFR TKIs induce significant tumor regression in NSCLC patients, but only in patients that harbor somatic mutations in exons of EGFR that code for the tyrosine kinase domain (~15-35% of NSCLC patients)." (PMID 27738319, 2016). "We next examined the impact of EGFR TKIs on tumor cell proliferation and apoptosis through immunohistochemistry." (PMID 26646697, 2016). "Nimotuzumab can trigger receptor-mediated internalization from cellular membrane to cytoplasm in EGFR-positive tumor cells." (PMID 26988752, 2016). "Mutational analysis of the kinase domain of EGFR coding sequence (exons 18 to 21), exon 2 of K-RAS, exons 9 and 20 of PI3KCA, and exon 15 of B-RAF was performed in primary tumor, and in MT-CHC01 cell line." (PMID 26486326, 2016). "dsRBEC shows high affinity towards EGFR and triggers ligand-induced endocytosis of the receptor, thus leading to the selective internalization of polyIC into EGFR over-expressing tumor cells." (PMID 27598772, 2016). "Cdc25A thereby regulates the EGFR-promoted Warburg effect, tumour cell proliferation and tumorigenesis." (PMID 27485204, 2016). "EGFR plays a role in cell survival signals as well as in epithelial to mesenchymal transition of tumour cells, angiogenesis and subsequent metastasis." (PMID 26870997, 2016). "EGFR-dependent regulation of glucose uptake has been observed in tumor cells, and EGFR has been shown to prevent autophagic cell death by maintaining intracellular glucose levels through interaction with and stabilization of SGLT1." (PMID 27851758, 2016). "In our selection of EGFR TKI resistant NSCLC patients with paired tumor rebiopsies, we detected CTCs in 6 of 7 samples with CTC counts less than 10 in each specimen." (PMID 26924553, 2016). "EGFR cell surface expressions in vitro by flow cytometric analysis and ex vivo by ELISA in tumor lysates were concordant." (PMID 27602494, 2016). "Therefore, the predictive power of EGFR mutations based on the primary tumor could be lessened, and rebiopsy from the metastatic sites, collecting circulating cancer cells or cell-free DNA for EGFR analysis should be considered, especially from the non-responsive sites." (PMID 27070580, 2016). "CTC positivity based on the mRT-PCR was strongly depending on tumour burden, enabling the possibility to serve as a disease and therapy resistance monitoring test, especially perhaps among EGFR positive NSCLC patients." (PMID 27302574, 2016). "In our study, EGFR and K-ras changed from WT to mutant type and vice versa within the primary tumor and metastases in some patients." (PMID 27070580, 2016). "These h528 scFv multimers were produced via a bacterial expression system, and after fractionation they inhibited tumor cell growth by blocking the EGFR phosphorylation in a multimerization‐dependent manner." (PMID 27419062, 2016). "Previously, we identified integrin α5 as a tumor suppressor via the negative regulation of EGFR signaling." (PMID 27641064, 2016). "Screening NSCLC patients for activating EGFR mutations is now clinical routine and there are three generations of EGFR inhibitors to treat therapy-naive or drug-resistant tumours." (PMID 27350784, 2016). "In this study we applied the anti-EGFR nanobody 99mTc-D10 for visualizing small tumour lesions with volumes below 100 mm3 by targeting EGFR in orthotopic human mammary MDA-MB-468 and MDA-MB-231 and subcutaneous human epidermoid A431 carcinoma mouse models." (PMID 26912069, 2016). "PFL-mediated downregulation of integrin and EGFR contributes to the inhibition of tumor growth in vitro and in vivo." (PMID 26850110, 2016). "Further investigation of necitumumab with oxaliplatin-based chemotherapy in patients with tumours wild type for RAS is required if this EGFR mAb is to be added to the therapeutic armamentarium of mCRC." (PMID 26766738, 2016).
tumor (continued). "The commercially available CellSearch® Tumor Phenotyping Reagent Epidermal Growth Factor Receptor (EGFR) kit (Veridex LLC, Raritan, NJ, USA) was used on the fourth channel of fluorescence of the CellSearch® system following the manufacturer’s instructions." (PMID 27465596, 2016). "Four neoplasms were weakly immunostained for ROS1, and two neoplasms were weakly immunostained for L858R-specific EGFR." (PMID 26974543, 2016). "Increasing the 89Zr-imgatuzumab dose to 160 μg, mitigated sEGFR competition for tumor bound EGFR, resulting in higher tumor uptake." (PMID 27602494, 2016). "This led to the development of novel agents targeting specific structures on the tumor membrane, such as EGFR or HER2." (PMID 28050231, 2016). "At recurrence, it progressed to GBM, with the typical features of this tumor type (amplification of EGFR, gain at chr7, and losses at chr9p24.3-p21.1, chr10p15.3-q26.3, chr13, and chr22)." (PMID 27172220, 2016). "ZEGFR:2377 was labeled with 111In for SPECT studies, and EGFR-expressing tumors were successfully imaged when the tracer specific activity was appropriately adjusted to reduce competing uptake in non-tumor tissues." (PMID 27388754, 2016). "Our aim was to examine the prevalence, clinicopathological associations as well as prognostic role of EGFR and HER2 protein expression and gene amplification in these tumours." (PMID 27387915, 2016). "EGFR is a crucial regulator in wound healing and tumor growth, and overexpressed EGFR was related to the process of ESCC infiltration in the early stages of carcinogenesis." (PMID 27966444, 2016). "In regards to cytologic tumor markers, only c-CYFRA was significantly different between EGFR status, with higher levels of c-CYFRA with EGFR mutations compared with wild-type EGFR (200.2 ng/ml ± 208.8 ng/ml vs 85.2 ng/ml ±135.8 ng/ml, p = 0.014)." (PMID 26979333, 2016). "Taken together, our results reveal a critical role for miR-218-5p as a tumor suppressor in NSCLC carcinogenesis which functions through the repression of EGFR translation." (PMID 27057632, 2016). "Intriguingly, CD44 has also been reported to function as a co-receptor for several growth factor receptors, such as EGFR and TGFβ receptor; their coupling is believed to be able to enhance the growth factor-driven tumor proliferation and/or metastasis." (PMID 26849234, 2016). "124I-Cetuximab clearly distinguished between tumours with high and tumours with low EGFR expression, demonstrating the in vivo specificity of the conjugate." (PMID 26627081, 2016). "The therapeutic efficiency of anti-EGFR, -HER2 and -c-MET antibodies, used alone or in combination, is associated with an increase of receptor ubiquitination and degradation in tumor cells, sometimes mediated by the E3 ubiquitin ligase CBL." (PMID 27203743, 2016). "A recent report on ABT-806, a humanised antibody that specifically targets epidermal growth factor receptor (EGFR), reports on cold competition blocking of the 806 antibody in A431 tumours." (PMID 26983636, 2016). "The epithelial component of tumor cells in our case showed immunoreactivity for all cytokeratin markers, EGFR, CD117, and VGEF." (PMID 27630780, 2016). "We detected EGFR cytoplasmic expression in our cohort of tumours with variable distributions and intensity, where LGSCs showed the highest level of expression." (PMID 26870997, 2016). "In conclusion, we have developed a bi-domain recombinant chimeric protein that is capable both of binding polyIC and of delivering it into EGFR over-expressing tumors, inducing tumor cell death." (PMID 27598772, 2016). "Our data support the notion that PI3K activation is a dominant pathway of Ras tumor progression, and is therefore an attractive target for increased efficacy in therapeutic intervention of H-Ras- and EGFR-mutant cancers." (PMID 27239960, 2016). "EGFR amplification status was known for all patients: EGFR was amplified in 27/59 (46%) tumor samples." (PMID 26637806, 2016).
tumor (continued). "The diversity of nanobodies binding specifically [in this case to EGF receptor (EGFR)] should allow for efficient targeting of different tumor antigens by enhanced attachment (in this case increased binding of nanobody-targeted vesicles to the EGFR)." (PMID 27542385, 2016). "Tumor cells with low Ki-67 but high EGFR expression would still exhibit high proliferation activities, and lead to a worse survival outcome." (PMID 26930401, 2016). "Their function is tightly monitored in normal cells but the oncogenic mutation of the RAS gene, which creates constitutively active RAS proteins, result in uncontrolled proliferation or survival in tumor cells and resistance to anti-EGFR drugs." (PMID 27248177, 2016). "EGFR expression was analysed in tumours from three independent patient cohorts; cohort 1 (n = 533), cohort 2 (n = 259) and cohort 3 (n = 310), previously analysed for immunohistochemical PODXL expression and KRAS and BRAF mutations (cohort 1 and 3)." (PMID 27160084, 2016). "Panitumumab is a complex which inhibits the expression of downstream molecules indirectly by binding to EGFR, so as to inhibit the proliferation and differentiation of tumor cells." (PMID 27806321, 2016). "Only those patients with low clinical tumor and nodal stages and low expression of EGFR, CK5/6 and Ki-67 had better prognosis." (PMID 26930401, 2016). "After combining the seven studies that examined tumor size, we also observed a statistically significant effect of high EGFR levels on tumor sizes ≥4 cm, with a combined OR of 1.64 (95% CI: 1.20–2.23) and no significant heterogeneity (I2 = 0.00%, Ph = 0.935)." (PMID 27438047, 2016). "The tumour sample from patient #8 showed a remarkable amplification of EGFR (>50 fold), likely due to a double minute chromosome as observed in many other GBM cases." (PMID 27843499, 2016). "To be able to detect even minor subclones in a background of cells with unmutated EGFR and RAS, we used state-of-the-art targeted NGS technology for highly sensitive and specific identification of mutations in a heterogeneous tumor." (PMID 27119512, 2016). "To demonstrate the ability to image multiple biomarkers simultaneously, we stained various tumor xenografts with an equimolar mixture of three NP flavors - EGFR-NPs, HER2-NPs and isotype-NPs." (PMID 26878888, 2016). "We designed a chimeric protein vector, dsRBEC, for the targeted delivery of polyIC to EGFR over-expressing tumor cells." (PMID 27598772, 2016). "microRNA-7-5p (miR-7-5p) is a tumor suppressor in multiple cancer types and inhibits growth and invasion by suppressing expression and activity of the epidermal growth factor receptor (EGFR) signaling pathway." (PMID 27203220, 2016). "In a next set of experiments, NK cells were combined with cetuximab and this was shown to enhance the lysis of EGFR+++ RASwt tumor cells." (PMID 27314237, 2016). "Our EGFR single-gene test had greater analytical sensitivity than NGS, detecting mutations in samples with well under 10% tumor." (PMID 27043212, 2016). "By univariate analysis, adenocarcinoma patients harboring EGFR mutations had DFS and OS significantly associated with clinical stage, tumor size, regional lymph node (LN) metastasis, adjuvant treatment, CEA, and Cyfra21-1." (PMID 27072585, 2016). "Osimertinib provides an effective treatment option for NSCLC patients with EGFRm-positive tumours that have relapsed while on EGFR TKI therapy due to T790M." (PMID 27861144, 2016). "Several miRNAs were described as experimentally direct regulators of EGFR, acting as tumor suppressors in various tumor types." (PMID 26646588, 2016). "EGFR inhibitors commonly produce a cytostatic effect with arrest in the G1 phase of the cell cycle, which can prevent tumor cell repopulation post-radiation." (PMID 27245053, 2016).